IL33 (interleukin 33)
Diseases named in the same sentence as IL33 in open-access papers (continued):
Sharing a sentence is not in itself a finding about the gene and the disease.
breast cancer (continued). "IL-1, generated by immune cells such as macrophages and lymphocytes, is released downstream of oncogenes in breast cancer, triggering an inflammatory response by stimulating other pro-inflammatory cytokines such as IL-6, tumor necrosis factor (TNF), and IL-33 (an early warning cytokine)." (PMID 41596472, 2026). "Similarly, research conducted in our country examined the relationship between IL-33, IGM, and breast cancer, revealing significantly elevated IL-33 levels in both diseases compared to controls." (PMID 39941611, 2025). "A proper understanding of this duality is essential for the development of strategies that shift the balance towards effective antitumor immunity, paving the way for usage of IL-33/ST2 signalling axis as both a biomarker and a therapeutic target in personalized breast cancer treatment." (PMID 41284319, 2025). "Increased expression of IL-33 and ST2 has been detected in breast cancer tissues compared with surrounding normal tissue, although the prognostic implications remain unclear." (PMID 41284319, 2025). "Based on these results, we assessed IL-33 expression using the luciferase gene, which is 4T1/LM4 cell-specific, as a loading control and found that IL-33 expression was higher in metastases-bearing lungs compared to that in the primary mammary tumors." (PMID 35805039, 2022). "Immunofluorescence analysis demonstrated that IL-33 expression was observed in both the metastases-bearing lungs and the primary mammary tumors but not in the normal lungs." (PMID 35805039, 2022). "In our study, the fluorescence intensity of IL-33 was significantly elevated in the lungs and primary mammary tumors of 4T1/LM4 tumor-bearing mice but not in the lungs of tumor-free mice." (PMID 35805039, 2022). "Patients with colorectal adenocarcinoma, multiple myeloma, breast cancer, and lung cancer also showed a negative correlation of IL-33 expression levels with tumor stage." (PMID 34209038, 2021). "In a mouse model for breast cancer, administration of exogenous IL-33 increased NKp461+ PD-1+ cell population, but not in ST2-deficient mice." (PMID 34209038, 2021). "Similarly, the Cancer Genome Atlas (TCGA) data showed that IL-33 and LPIN1 expression levels were positively correlated in the breast cancer patients." (PMID 33946554, 2021). "Similarly, the IL-33/ILC2 axis also accelerates tumor growth and promotes lung and liver metastasis by recruiting MDSCs to produce IL-13 in a mouse model of breast cancer, acute promyelocytic leukemia (APL), and prostate cancer." (PMID 32117199, 2019). "Finally, serum IL-33 was used in differential diagnoses of idiopathic granulomatous mastitis (IGM) and breast cancer." (PMID 30205617, 2018). "Moreover, knockdown of IL-33, ST2 and COT significantly reduced the tumorigenicity of breast cancer cells." (PMID 30205617, 2018). "Patients with breast cancer have higher serum levels of IL-33 compared to patients with benign breast diseases and IL-33 expression was more pronounced in breast tumors than in normal breast tissue." (PMID 26919112, 2016). "Our ELISA results showed that PDGF-C level was elevated in the sera from patients with breast cancer and that serum levels of IL-33 and sST2 in breast cancer patients had significant correlations with PDGF-C, which indicated the diagnosis and prognosis value of IL-33 and sST2." (PMID 26456994, 2015). "IL-33 and sST2 were positively correlated with VEGF, MMP-11, and PDGF-C in breast cancer patients." (PMID 26456994, 2015). "Murine breast carcinoma models suggest disruption of ST2 signaling may enhance the anti-tumor immune response, suggesting IL-33 impedes anti-tumor immunity." (PMID 24778632, 2014). "Although the mechanism has not been fully elucidated, it is considered that IL-33 could induce specific properties of breast cancer stem cells." (PMID 37762328, 2023).
breast cancer (continued). "Several studies suggested that IL‐33 could be considered as a tumour biomarker; IL‐33/ST2 signalling have a pro‐tumourigenic role in head and neck squamous cancer, breast cancer, non‐small‐cell lung cancer, cholangiocarcinoma, gastric cancer and myeloproliferative neoplasm." (PMID 35344301, 2022). "In a murine model with 4T1 breast cancer cell implantation, the administration of IL-33 induced the recruitment of NK cells in the lungs, by means of the production of CCL5 by eosinophils and CD8+ T cells, and NK cells activation, through the increase of ST2 expression (receptor for IL-33)." (PMID 34572273, 2021). "Treatment with propranolol also reduced an IL-33-mediated increase in the number of MCF-7 cell colonies in the soft agar assay, indicating that LPIN1 induced by the COT/JNK1/2 pathway is essential for anchorage-independent proliferation of breast cancer under IL-33 stimulation." (PMID 33946554, 2021). "Therefore, we hypothesized that IL-33 could play a role in tumour occurrence by influencing the TME, similar to its role in breast cancer." (PMID 33308251, 2020). "Indeed, ILC2-derived IL-33 promotes tumor formation and metastasis in breast cancer by upregulating Treg cells through inducible co-stimulator (ICOS)/ICOS ligand (ICOSL) interaction, whereas IL-33 also activates ILC2s to recruit eosinophils through ICOS/ICOSL interaction during lung inflammation." (PMID 32117199, 2019). "However, the detailed role of IL-33 and sST2 in the metastatic process of breast cancer has not been explored." (PMID 26456994, 2015). "In the present study, we examined whether the lack of IL-33/ST2 signaling affects antitumor immunity in an experimental murine model of mammary carcinoma." (PMID 21484786, 2011). "On the basis of these observations we suggest that IL-33 released by necrotic cells may facilitate VEGF expression on nearby tumor cells, which could lead to enhanced angiogenesis as demonstrated by high-grade MVD in perinecrotic zone in human breast cancer tissue." (PMID 26919112, 2016). "However, the role of IL-33 in patients with breast cancers (BC) is not elucidated." (PMID 24778632, 2014). "Finally, in a recent report, suppression of breast cancer progression and metastasis was observed in a murine breast cancer model wherein mice lacked the IL-33 signaling receptor, ST2, further supporting the role of the IL-33/ST2 axis in tumor formation and the progression of cancer." (PMID 23062310, 2012). "We found significantly higher expression of IL-33, IL-33R and VEGF in breast cancer tissues with absent tumor necrosis." (PMID 26919112, 2016). "Furthermore, administration of IL-33 to wild type mice significantly reduced the cytotoxic activities of NK cells but not CD8+ T cells, although mammary tumor progression was unaffected when CD8+ T cells were depleted in vivo." (PMID 30205617, 2018).
rheumatoid arthritis (103 papers, 2008 to 2025). A chronic, systemic autoimmune disorder characterized by inflammation in the synovial membranes and articular surfaces. "Several studies have reported associations between IL33 rs7044343 polymorphism and autoimmune diseases, including rheumatoid arthritis, systemic sclerosis, and BD in Turkey." (PMID 33859633, 2021). "Comparison of the IL-33 genotypes and alleles frequencies between patients diagnosed with rheumatoid arthritis, ankylosing spondylitis, psoriatic arthritis, and healthy subjects." (PMID 34177886, 2021). "IL-33 exacerbates disease progression in rheumatoid arthritis models associated with proinflammatory cytokine production, mast cell degranulation, and neutrophil recruitment." (PMID 33884963, 2021). "IL-33 is believed to be a therapeutic option for bone loss because IL-33 protected against bone loss in a rheumatoid arthritis mouse model." (PMID 32046264, 2020). "Strict regulation starts from nuclear localization and chromosome association of IL-33, where nuclear IL-33 functions as a transcriptional repressor when overexpressed in chronically in?amed tissues from patients with rheumatoid arthritis and Crohn's disease." (PMID 30619376, 2018). "A recent study has demonstrated an association of circulating IL-33 levels with the progression of carotid atherosclerotic plaques in rheumatoid arthritis patients." (PMID 27142573, 2016). "Interleukin-33 (IL-33), an IL-1 family nuclear cytokine, plays an important role in many inflammatory disorders, which include rheumatoid arthritis, allergic rhinitis, and others." (PMID 39452748, 2024). "Conversely, HIF-1α can reduce ILC2 responsiveness to IL-33 and even further exacerbate IL-33 production in rheumatoid arthritis, making it a target of drug treatment and indicating that this proinflammatory-hypoxic crosstalk is bidirectional." (PMID 37375100, 2023). "IL-33 treatment significantly worsens rheumatoid arthritis, whereas antagonizing IL-33 signaling decreased disease severity in a mouse collagen-induced arthritis model." (PMID 36291105, 2022). "IL-33 is also a crucial regulator of inflammation in rheumatoid arthritis patients and mouse models alike, wherein it activates TNF pathways in fibroblasts." (PMID 35439171, 2022). "IL-33 is also a potent inducer of mucosal IgM+ IL-10-producing regulatory B cells in mice, and IL-33 level correlates with increased plasma total IgM and auto-reactive antibodies in rheumatoid arthritis patients." (PMID 36362246, 2022). "In mouse models of rheumatoid arthritis, IL-33 administration worsened the disease pattern, whereas antagonizing IL-33 signaling significantly decreased disease activity." (PMID 35328556, 2022). "Analysis of the IL-33 genotypes distributions with regard to therapeutic response to anti-TNF agents in rheumatoid arthritis, ankylosing spondylitis and psoriatic arthritis patients." (PMID 34177886, 2021). "The IL-33/serum stimulation-2 (ST2) axis has been shown to have a detrimental effect on rheumatoid arthritis, systemic lupus erythematosus, and other rheumatic diseases." (PMID 34589505, 2021). "Analysis of the IL-33 genotypes distributions with regard to baseline clinical parameters of rheumatoid arthritis, ankylosing spondylitis and psoriatic arthritis patients." (PMID 34177886, 2021). "Gender-stratified analysis of the IL-33 genotypes frequencies in rheumatoid arthritis, ankylosing spondylitis, and psoriatic arthritis patients." (PMID 34177886, 2021). "Different human disorders involve IL-33 as a potent trigger of inflammatory processes, such as Rheumatoid Arthritis, Systemic Sclerosis, Sjörgen Disease and Psoriasis." (PMID 33133101, 2020). "They finally compared these levels with those in patients with rheumatoid arthritis, finding higher levels of IL-33 in the serum and SF of PSA." (PMID 31736655, 2019). "In patients with rheumatoid arthritis IL-33 is higher compared to controls and it positively correlates to bone erosions." (PMID 30846811, 2019).
rheumatoid arthritis (continued). "Genetic dysregulation of the IL-33/ST2 axis significantly increases the predisposition toward development of inflammatory bowel disease, systemic sclerosis, rheumatoid arthritis and systemic lupus erythematosus." (PMID 30574145, 2018). "In rheumatoid arthritis as well as lupus patients, increased serum levels of IL-33 have been shown to correlate with autoantibody levels, including anti-Sjögren's syndrome type B, rheumatoid factor, anti-citrullinated antibodies, among others." (PMID 30574145, 2018). "IL-33 levels were elevated in sera and synovial fluid samples of rheumatoid arthritis (RA) patients and were correlated with the activity of the disease." (PMID 29180837, 2017). "In rheumatoid arthritis (RA) patients, IL-33 levels are elevated in serum and synovial fluid and strong IL-33 expression can be detected in endothelial cells and fibroblasts in the human RA synovium." (PMID 27317338, 2016). "Blockade of IL-33/ST2 interaction resulted in dramatically attenuated disease severity of rheumatoid arthritis." (PMID 26675669, 2015). "In rheumatoid arthritis, a higher level of IL-33 was detected in synovial fluid, serum, and was correlated with disease activity compared to moderate or low activity group or healthy controls." (PMID 26675669, 2015). "In the synovial fibroblasts of patients with rheumatoid arthritis, IL-33 was detected and was markedly upregulated by the addition of TNF-α and IL-1β." (PMID 26557152, 2015). "Taken together, these data imply that the IL-33/ST2 pathway plays a critical role in the pathogenesis of rheumatoid arthritis." (PMID 25032216, 2014). "The expression and correlation of IL-33 and sST2 in rheumatoid arthritis (RA) are of great interest." (PMID 24106520, 2013). "In human rheumatoid arthritis (RA), IL-33 levels in serum and synovial fluid are elevated and strong IL-33 expression can be detected in endothelial cells and fibroblasts in human RA synovium." (PMID 23324173, 2013). "Our unpublished data showed that IL-33 displayed key regulatory features of the biological activities of rheumatoid arthritis synovial fibroblasts." (PMID 23967327, 2013). "Until now, there has been much evidence confirming the involvement of IL-33 in rheumatoid arthritis." (PMID 24151520, 2013). "Knocking down HIF-1α compromised IL-33 expression in rheumatoid arthritis synovial fibroblasts (RASF), while enforcing HIF-1α expression in RASF substantially upregulated IL-33 levels." (PMID 23967327, 2013). "Here, we will review the role of IL-33 in the pathogenesis of several clinical rheumatic diseases, mainly including rheumatoid arthritis, systemic lupus erythematosus, and ankylosing spondylitis." (PMID 24151520, 2013). "In situ hybridization studies also indicated that endothelial cells constitute a major source of IL-33 in chronically inflamed tissues from patients with rheumatoid arthritis and Crohn's disease." (PMID 18836528, 2008). "For instance, interleukin-33 (IL-33), which has been the subject of study in rheumatological autoimmune diseases such as rheumatoid arthritis and systemic lupus erythematosus (SLE), has demonstrated increased levels and roles in cytokine synthesis and the inflammatory response." (PMID 39941611, 2025). "As for IL‐33, the boosting of cytokine production by MCs and IgG‐mediated responses is consistent with what has already been observed in experimental models and in disease, such as in rheumatoid arthritis." (PMID 40926620, 2025). "IL‐33 is hardly detected in mouse blood vessels during homeostasis, whereas human endothelial cells are known to express IL‐33 constitutively and to be a major source of IL‐33 mRNA in inflamed tissues from patients with rheumatoid arthritis, psoriasis and Crohn's disease." (PMID 39654685, 2024). "In addition to cells of the immune system, CD36 and IL-33 are also found in human OA cartilage and rheumatoid arthritis (RA) synovium, respectively." (PMID 33374841, 2020).
rheumatoid arthritis (continued). "Also, in patients with rheumatoid arthritis, higher levels of IL-33 were correlated with more severe disease, and blockage of IL-33/ST2 signaling ameliorated murine collagen-induced arthritis associated with decreased IFNγ production." (PMID 30213101, 2018). "However, endothelial cells have been described as the major cellular source of IL-33 in chronically inflamed tissues under other pathological conditions such as rheumatoid arthritis and Crohn's disease." (PMID 27150562, 2016). "Extracellular IL-33 has also been detected in human blood and synovial fluids in pathological conditions, where cells have been damaged (during rheumatoid arthritis or infection with influenza virus, respectively) and in mouse peritoneal and bronchoalveolar lavage fluid." (PMID 26425339, 2015). "More recently, IL-33 has been shown to change the symptoms of rheumatoid arthritis, systemic lupus erythematosus, and other autoimmune diseases, which may elicit beneficial or detrimental effects depending on the disease setting." (PMID 25032216, 2014). "IL-33 has been shown to participate in the acute-phase response and to be involved in the pathogenesis of several diseases, including allergic respiratory diseases, rheumatoid arthritis and systemic lupus erythematosus." (PMID 23423835, 2012). "As a pleiotropic cytokine, the involvement of IL-33 in autoimmune diseases such as in rheumatoid arthritis (RA), inflammatory bowel diseases (IBD), and systemic lupus erythematosus (SLE) has been described." (PMID 33182616, 2020). "It has been reported that IL-33 was expressed in synovial fibroblasts from patients with rheumatoid arthritis (RA), and expression was markedly elevated in vitro by TNFα and IL-lβ stimulation." (PMID 30863362, 2019). "According to recent studies, increased IL-33 and sST2 levels have been observed in patients with infections, cardiovascular disorders, allergic diseases, and rheumatic diseases such as systemic lupus erythematosus, rheumatoid arthritis (RA), Wegener's granulomatosis, and Behcet's disease." (PMID 30498500, 2018). "We aimed to study the possible association between serum IL-33 detection and response to rituximab (RTX) in rheumatoid arthritis (RA) patients in different cohorts with an accurate enzyme-linked immunosorbent assay (ELISA)." (PMID 27964756, 2016). "In the synovium of rheumatoid arthritis (RA) patients, elevated levels of IL-33 and sST2 were detected." (PMID 24692848, 2014). "Interleukin (IL)-33 is a proinflammatory cytokine contributing to the pathogenesis of rheumatoid arthritis (RA)." (PMID 24779919, 2014). "Aberrant expressions of IL-33 and/or ST2 has been well documented in plentiful inflammatory disorders, such as systemic lupus erythematosus, rheumatoid arthritis, multiple sclerosis, and inflammatory bowel disease." (PMID 39713054, 2024). "For instance, IL-33 and ST2 levels are significantly increased in both the serum and synovium of patients with rheumatoid arthritis, the archetype of inflammatory rheumatic diseases, and even correlated with disease activity." (PMID 35328556, 2022). "Much current interest in IL-33 has been prompted by its role in several inflammatory and autoimmune diseases including SLE, Sjögren’s syndrome, systemic sclerosis and rheumatoid arthritis." (PMID 35328556, 2022). "IL-33 and ST2 levels in both the serum and synovium of patients with rheumatoid arthritis, systemic sclerosis, and systemic lupus erythematosus are significantly increased, and levels are correlated with disease severity." (PMID 36291105, 2022). "IL-33 is involved in the pathogenesis of rheumatoid arthritis (RA)." (PMID 33490289, 2020). "A similarly complex role of IL-33 is found in rheumatoid arthritis (RA)." (PMID 30949175, 2019). "It is involved in the pathogenesis of rheumatoid arthritis (RA) and its models; we recently demonstrated that exogenous IL-33 could inhibit collagen-induced arthritis (CIA) in C57BL/6 mice." (PMID 27317338, 2016).